RNU7-20P (RNA, U7 small nuclear 20 pseudogene)
Synonyms: U7.20
Gene: Small nuclear RNA gene on chromosome 7 (148,821,012 to 148,821,073, forward strand). Ensembl gene ENSG00000251712.
Homologues: Orthologues: macaque U7 (94% identical). Paralogues in human: RNU7-19P (92% identical), RNU7-7P (90% identical), RNU7-10P (87% identical), RNU7-14P (87% identical), RNU7-73P (87% identical), RNU7-1 (85% identical), RNU7-12P (85% identical), RNU7-21P (85% identical), RNU7-25P (85% identical), RNU7-27P (85% identical), RNU7-2P (85% identical), RNU7-34P (85% identical), and 140 more.